FOXP3 (forkhead box P3)
Diseases named in the same sentence as FOXP3 in open-access papers (continued):
Sharing a sentence is not in itself a finding about the gene and the disease.
tumor (continued). "CD8+ and FOXP3+ TIL densities as well as PD-L1 levels in tumor cells and lymphocytes, were assessed through immunohistochemical staining." (PMID 27683115, 2016). "Regulatory FoxP3+ T cells (Treg) have immune suppressive activity by inhibiting host anti-tumor responses." (PMID 27589686, 2016). "FOXP3+ cells were detected in 80 (95.2%) of the 84 assessable samples, although in 8 (10%) positive cells were only found in the tumor-near stromal compartment, and in one case (1.8%) positive cells were only found in the tumor compartment." (PMID 27463005, 2016). "The number of CD3+FoxP3+ Tregs infiltrating in the tumor epithelium (p < 0.0001) and stroma (p < 0.0001) was also significantly higher in HPV-positive tumors." (PMID 26899388, 2016). "The present study aimed to analyze two polymorphisms in FOXP3 and one polymorphism in CXCL12 in WT samples, in a search for new possible molecular markers to this childhood neoplasia." (PMID 27830498, 2016). "In CRC, a greater proportion of CD25+FoxP3+ TI Tregs expressed Ki67, compared with Tregs from tumor-free liver and peripheral blood, indicating efficient in situ proliferation." (PMID 27509527, 2016). "Higher Treg levels in tumour tissues indicated a worse prognosis, and the FOXP3+ Tregs/CD4+ T cells ratio was an independent prognostic factor for OS." (PMID 27725696, 2016). "The failure of immune responses against tumours has been attributed to an active suppression by CD4+FoxP3+CD25+ natural Tregs." (PMID 27341421, 2016). "The infiltration of Foxp3+ regulatory T (Treg) cells is considered to be a critical step during tumor development and progression." (PMID 27075020, 2016). "The elevated TGF-β1 levels were accompanied by increased Foxp3 expression in the lungs of 4T1/TGF-β1 tumor-bearing mice, which aroused our interest in the relationship between TGF-β1 production and the Treg population." (PMID 27036297, 2016). "The number of tumor infiltrating FOXP3+ regulatory T cells, especially as reflected by a decreased CD8+/FOXP3+ ratio, is reportedly associated with a poor prognosis for several cancer types." (PMID 27322149, 2016). "FoxP3+/–Helios+ Tregs are significantly expanded in the peripheral blood and at tumor sites of various cancers, and have been reported to exhibit enhanced in vitro suppressive activity." (PMID 26885615, 2016). "HCC cells did express higher CCL20 levels than non-tumour cells, and the main FOXP3+ Tregs assembled in CCL20 high-expressing area." (PMID 27725696, 2016). "As for the FOXP3 stroma/ CD8 tumor expression ratio, patients with high levels also presented worse PFS (23 vs. 37.8 months, p = 0.042) and OS (46.4 vs. 74.3 months, p = 0.025)." (PMID 27463005, 2016). "In combination with Gvax and the FOXP3 temporary inhibitor peptide P60 the bispecific aptamer induced higher T cell tumor infiltration, slower tumor growth, and longer survival." (PMID 27413756, 2016). "Knocking-down of Foxp3 expression blocks in vivo tumor growth in mice and prolongs mice's survival, which is associated with von Willebrand factor expression." (PMID 27557492, 2016). "All tumor-infiltrating FoxP3+ cells were CD25+ T cells, while 93.6 ± 8.8% of CD25+ T cells were FoxP3+ cells in the tumor tissue." (PMID 27177223, 2016). "Accumulating evidence indicates that FoxP3+ Treg cells can suppress tumor-specific immunity, which provides a clear rationale for development of immunotherapies that can modulate the influence of these regulatory cells." (PMID 27177223, 2016). "Strikingly, more CD3+ and Foxp3+ T lymphocytes were localized around tumor sites than in neighboring normal tissues in liver sections from HCC patients." (PMID 26824903, 2016). "Foxp3 specifies the Treg cell lineage and is crucial for immune tolerance against pathogens and tumour cells." (PMID 28074191, 2016). "CD4+CD25+FoxP3+ regulatory T cells (Tregs) and myeloid-derived suppressor cells (MDSCs) are the main cell types contrasting the effective anti-tumor cellular immunity." (PMID 26911136, 2016).
tumor (continued). "TGF-βs are also known to stimulate the conversion of CD4+CD25- T cells to CD4+CD25+Foxp3+ regulatory T-cells, which inhibit anti-tumor immunity." (PMID 27863384, 2016). "Regulatory T cells (Tregs), particularly CD4+CD25+Foxp3+ Tregs, down regulate immunity and promote tumor cell growth." (PMID 27389040, 2016). "Because previous studies have revealed that tumor-derived TGF-β1 mediates the conversion of CD4+Foxp3+ Tregs, we measured the percentage of CD4+CD25+Foxp3+ Tregs and CD103+CD4+Foxp3+ cells in lymphocytes from the spleens and lungs of tumor-bearing mice." (PMID 27036297, 2016). "The results show that INFα-2b inhibits cancer cell immune evasion by decreasing the levels of CD4+CD25+Foxp3+ Tregs and suppressing the expression of TGFβ and IL-10 in the tumor microenvironment." (PMID 27389040, 2016). "From the different combinations that were tested we observed that patients with a high FOXP3 stroma/ CD4 tumor expression ratio have reduced PFS (19.4 vs. 37.8 months, p = 0.013) and OS (46.6 vs. 81.2 months, p = 0.012)." (PMID 27463005, 2016). "The balance of CD8+ and FoxP3+ T-cells at the tumor border and in TLS provides prognostic information in patients with CRC PM." (PMID 27449756, 2016). "A higher FoxP3/CD8 ratio was significantly associated with ER negativity (p = 0.031 and <0.001 for invasive margin and tumor center), high proliferation (both areas p < 0.001) and tumor histological grade (p = 0.013 and 0.034, respectively)." (PMID 27473163, 2016). "Consistently, the density of von Willebrand factor (vWF) immunostaining is decreased in the Foxp3-knokcking down tumor xenografts, as compared with the control (p = 0.020)." (PMID 27557492, 2016). "The present study revealed, for the first time, that a high density of CD25+ (HR = 4.27) and FOXP3+ (HR = 6.05) T-cells in the tumor microenvironment was predictive of BCG failure." (PMID 27221038, 2016). "Our data showed a clear decrease in Nrp-1 obviously in IL10-deficient tumor-bearing mice, and the number of CD4+Foxp3+Nrp-1+ T cells obtained from the spleen was significantly decreased in IL10−/− B16/F10 mice based on flow cytometry analysis." (PMID 27075020, 2016). "It would be interesting to unravel in which steps of tumor induction and/or promotion is Runx1 and Foxp3 interplay defining cell fate." (PMID 26735887, 2016). "There was therefore a trend toward an improved ratio of CD8+ : FoxP3+ cells in αCD40-treated tumours (1.51 fold increase versus isotype, p=0.114)." (PMID 26918344, 2016). "Regulatory T (Tregs) cells play an important role in mediating tolerance to self-antigens but can also mediate detrimental tolerance to tumours and pathogens in a Foxp3-dependent manner." (PMID 28074191, 2016). "Overproduction of TGF-β1 in 4T1/TGF-β1 tumor-bearing mice was associated with a higher percentage of CD4+CD25+Foxp3+ cells in the lungs and CD103+CD4+Foxp3+ cells in the spleens, compared with 4T1/RFP tumor-bearing mice and tumor-free mice." (PMID 27036297, 2016). "Splenic CD4+Foxp3+ T cells and tumor CD4+Foxp3+ T cells obtained from IL-10−/− B16/F10 mice were significantly increased compared with WT mice." (PMID 27075020, 2016). "Foxp3+ Tregs have been shown to the essential suppressors of the anti-tumor responses by interfering with the release of cytolytic granule by cytotoxic T lymphocytes (CTLs)." (PMID 27153545, 2016). "Runx1 is able to promote RSPO3 gene expression and inhibit GJA1 gene expression on tumor epithelial cells, depending on Foxp3 availability." (PMID 26735887, 2016). "Dual staining with mouse anti BPVE2 and rabbit anti-FOXP3 confirmed that papillomavirus infected tumour cells co-expressed both antigens in their nuclei." (PMID 27160146, 2016). "It is in accordance with a recent study which verifies that increased Foxp3+ tumor infiltrating lymphocytes are related to increased serum albumin and better outcomes in stage II and III CRC." (PMID 27992611, 2016).
tumor (continued). "On the other hand, other types of immune cells, including macrophages and FOXP3+ Tregs, actually facilitated and promoted carcinogenesis and tumor growth." (PMID 27073890, 2016). "The results demonstrated that knocking-down of Foxp3 expression blocks in vivo tumor growth of T24-B cells in mice and prolongs the survival (p values, < 0.0001 and 0.0024, respectively)." (PMID 27557492, 2016). "Increased levels of FOXP3+ Tregs have been documented in blood, lymph nodes, and infiltrating various human tumours." (PMID 27777963, 2016). "Development of small molecule inhibitors of Foxp3 function is therefore considered a promising strategy to enhance anti-tumor immunity." (PMID 27284967, 2016). "Tumor-derived TGF-β1 has been showed to induce the expression of Foxp3, which is a firm link between TGF-β1 levels and Tregs." (PMID 27036297, 2016). "Basal-like tumors, and most remarkably their tumor centers, hosted the highest number of FoxP3+ T-cells with an unfavorable ratio to cytotoxic CD8+ T-cells." (PMID 27473163, 2016). "Foxp3+CD4+ T cells from the tumor environment show upregulation of cell-surface markers, including CTLA4, TIM3, and PD1, as well as a variety of chemokine receptors and suppressive cytokines." (PMID 27999575, 2016). "By contrast, FOXP3+ TILs, which diminish the immune response to self-antigens, have a critical role in suppressing anti-tumor immunity." (PMID 26341640, 2015). "Our large meta-analysis comprehensively reviewed 76 studies on the prognostic significance of tumor-infiltrating FoxP3+ Tregs in 17 types of cancer (15512 cancer cases)." (PMID 26462617, 2015). "These correlations were practically similar for the number of CD3+FoxP3− T cells, because the number of FoxP3+ cells infiltrating in the tumor epithelium was relatively low." (PMID 25795131, 2015). "We see a significant increase in intraepithelial FOXP3 staining for the ID8 tumor compared to the stromal compartment, despite a decrease in CD4 staining suggesting enrichment of the regulatory T cells in the intraepithelial compartment." (PMID 25992288, 2015). "In particular, FOXP3 dramatically induced the expression of miR-146a/b that prevented tumor cell proliferation while also enhancing apoptosis." (PMID 26682271, 2015). "It has been clear that FoxP3+ Treg-induced immune suppression is the major obstacle for successful anti-tumor immunity." (PMID 25968569, 2015). "CD8+ TIL, the CD8/FOXP3 ratio, unstained TILs, residual tumor size, nodal status after NAC, and basal-like type were significantly correlated with RFS in univariate analyses." (PMID 26341640, 2015). "The aim of this study was thus to firstly evaluate the frequencies of CD4+CD25+Foxp3+ Treg cells in tumor tissue as well as in peripheral blood in patients with NIP and SSCC." (PMID 26020249, 2015). "The stratified analysis suggested the molecular subtype and tumor stage significantly influenced the prognostic value of FoxP3+ Tregs in certain types of cancer." (PMID 26462617, 2015). "Tumor-induced FOXP3 + regulatory T cells increasing indicates a potential barrier to attempts at cancer immunotherapy." (PMID 26475790, 2015). "According to the FOXP3-positive regions, the examined studies were categorized into 3 subgroups, namely intratumoral lymphocytes, peritumoral lymphocytes, and/or a tumor cell subgroup." (PMID 26305693, 2015). "A subpopulation of CD4+ T cells that express CD25 and the master transcriptional factor Foxp3, termed regulatory T cells (Tregs), play a crucial role in promoting tumor growth and progress by inhibiting anti-tumor CD8+ T cells." (PMID 26451607, 2015). "FoxP3+Helios+ Tregs are significantly expanded in circulation and tumor microenvironment in various cancers including colorectal cancer, renal cell carcinoma and glioblastoma." (PMID 26343373, 2015). "In the recent past, for instance, several studies have shown an important role of CD8+Foxp3+ Tregs in tumor immune evasion." (PMID 26317902, 2015).
tumor (continued). "In fact, the NF-κB inhibitor bortezomib induced apoptosis in prostate epithelial cells of Foxp3cKO mice, suggesting that NF-κB-related apoptosis is involved in FOXP3-mediated tumor suppression." (PMID 26682271, 2015). "After migrating to tumor site, Foxp3+CD4+ T cells can inhibit the activity of cytotoxic T cells through cell-to-cell contact." (PMID 26604855, 2015). "We found that most tumor-infiltrating CD4+ T cells were Foxp3+ Tregs (around 70% in E0771 tumors), and there were very few Th17 and Th2 cells in the tumor stroma." (PMID 25760243, 2015). "Immune suppression in the tumor microenvironment is fundamentally mediated by CD4+CD25+FoxP3+ regulatory T cells (Tregs), as the major mechanism of tumor immune escape, a crucial hurdle for tumor immunotherapy." (PMID 26029105, 2015). "The staining was performed using an antibody directed against a marker of endothelial cells, CD31, as well as for cytofluorimetric assessment of the level of tumor-infiltrating Treg lymphocytes (CD4+CD25high+Foxp3+)." (PMID 25801067, 2015). "Because chronic inflammation is one of the critical processes promoting carcinogenesis and tumor growth, Foxp3+CD4+ T cells are able to down-regulate the pro-tumorigenic inflammatory responses." (PMID 26604855, 2015). "The expression of chemokine receptors binding the tumour signature chemokines defined above was compared on Foxp3+ and Foxp3− CD4+ T cells." (PMID 25495686, 2015). "In conclusion, the present study reported for the first time a subset of FOXP3+CD3+CD56+ cells spontaneously arising in the tumor mass of HCC patients." (PMID 26437631, 2015). "The frequency of CD4+ Foxp3+ regulatory T (Treg) cells is often significantly increased in the blood of tumour-bearing mice and people with cancer." (PMID 25495686, 2015). "Responsiveness to treatment is accompanied by increasing densities of OX40+ CD8+ T cells within the tumor tissue and decreasing FOXP3+ Treg infiltration." (PMID 26439988, 2015). "In previous studies, the correlation of the number of CD4+CD25+Foxp3+ Tregs in TDLNs with tumor stage and survival was contradictory." (PMID 25990075, 2015). "COX-2 inhibitor attenuates Treg cell activity and Foxp3 expression in tumor-infiltrating lymphocytes and enhances antitumor responses, which still delays primary tumor growth and reduces MDSC accumulation." (PMID 26549987, 2015). "Evidence from murine and human studies suggests that expression of PD-L1 and the presence FoxP3+ regulatory T cells can reduce the anti-tumor effect of ACT." (PMID 26500776, 2015). "The expression of Foxp3 mRNA in spleen, thymus, and tumor was also significantly downregulated in the FYN group." (PMID 26161392, 2015). "There was a strong positive correlation between the pixel count of Tbet+ and Foxp3+ cells (r = 0.539, p < 0.0005; Pearson) indicating that these cell types frequently co-infiltrated the tumor." (PMID 26357849, 2015). "Especially FOXP3+T-cells and M2-polarized macrophages have been shown to have an anti-inflammatory function and to suppress anti-tumor immunity thus promoting tumor cell survival." (PMID 25669968, 2015). "On the other hand, when treating cancers and infectious diseases, therapeutic modalities should avoid the generation and/or expansion of FoxP3+Helios+ Tregs to avoid compromising anti-tumor or anti-microbial immune responses." (PMID 26343373, 2015). "Although the reason for the discrepancy remains elusive, it questions to what extent TGF-β1 is responsible for the accumulation of FOXP3+CD3+CD56+ cells in the tumor tissue." (PMID 26437631, 2015). "The densities of CD8, CD45RO, and FOXP3 in the cores of the tumor center were 119.9, 201.8, and 50.8, respectively, and those in the invasion front were 138.3, 177.7, and 58.6, respectively." (PMID 25875774, 2015). "In patients with ovarian carcinoma, the host response to the tumor has been shown to be inhibited by Foxp3+CCR4+ Tregs recruited to the tumor by CCL17 and CCL22." (PMID 26197455, 2015).
tumor (continued). "Conversely, FOXP3-mediated inhibition of cell proliferation and tumor growth and its induction of apoptosis were partially blocked by miR-146a/b inhibitors, indicating a contribution of miR-146a/b to FOXP3-triggered tumor suppression." (PMID 26682271, 2015). "It has been shown that PD-1 expression on CD4+ effector T cells and the presence of CD4+Foxp3+ Tregs suppress anti-tumor responses." (PMID 25851535, 2015). "T regulatory cells (Tregs) in periphery as well as in tumor area express more of Foxp3 and specifically inhibit CD8 T cell activity, thereby blocking virus-specific immune responses and leading to viral persistence." (PMID 25767469, 2015). "The results indicate that high level of CD14, ARG1, and FOXP3 mRNA expression in primary NB tumor significantly correlated to a better survival." (PMID 26161395, 2015). "One possible approach to treating patients with high tumor PD-L1 expression and associated low CD8:Foxp3 T-cell ratios is the addition of immune-stimulatory molecules, such as agonists of CD27, GITR, 4-1BB, OX40 and others." (PMID 26317902, 2015). "Although never examined in the context of RCC, the ratio of cytotoxic CD8+ T-cells to Foxp3+ T-cells has been evaluated in other tumor types in the context of clinical outcome." (PMID 26317902, 2015). "As expected, Foxp3+CD4/CD8 ratios were dramatically increased with the tumor progression in both tumor models." (PMID 25968569, 2015). "Gene expression of CD4 and FOXP3 showed minimal variability between tumours in all examined profilers and were excluded from further cluster analysis." (PMID 25970543, 2015). "Tumor-infiltrating Foxp3+CD4+ T cells were observed in the tumor stroma as well as tumor islets with predominant infiltration in the tumor stroma." (PMID 26604855, 2015). "Whereas in E0771-bearing mice, only CD4+IL17+ and CD4+Foxp3+ subsets had significant increases in tumor draining lymph nodes." (PMID 25968569, 2015). "CD4+CD25+Foxp3+ Tregs were considered as a crucial factor that suppress the anti-tumor function of Effector CD8+ T cells." (PMID 26451607, 2015). "It’s reported that in early tumor stages, Th1 cells are the dominant population of CD4+ T cells, perhaps important for immunosurveillance; while in the advanced tumor stages, FoxP3+ Treg and Th17 cells become the dominant populations." (PMID 26587366, 2015). "It has been well studied that preS2 works as a promoter of HCC by activating oncogenes, including hTERT and Foxp3 or triggering the activation of tumor-promoting signaling." (PMID 26315112, 2015). "In mice vaccinated with ENO1 or OVA, the percentage of FoxP3+ Treg cells in total CD4+CD25+ cells of spleens from tumor-bearing mice was significantly increased compared to those from tumor-free mice." (PMID 26551021, 2015). "From immunohistochemical analysis, tumor-infiltrating CD4+FoxP3+ Tregs were decreased while tumor-infiltrating CTLs were increased in all experimental groups especially in combination groups compared with those of the control group." (PMID 26683520, 2015). "In recent years, Foxp3 expression in tumor cells (cancer cell-derived Foxp3) has gained great interest, but its function and molecular mechanisms remain incompletely understood." (PMID 25779374, 2015). "Better survival was found for NSCLC patents with higher Foxp3+CD4+ T cells infiltration in tumor islets, stroma or higher total Foxp3+CD4+ T cells infiltration (P < 0.05)." (PMID 26604855, 2015). "A cytotoxic tumor microenvironment, defined by a CD8+/FOXP3+ ratio >1.5 was associated with higher numbers of CD68+pSTAT1+ (P=0.025) and CD163+pSTAT1+ macrophages (P<0.0005)." (PMID 25978381, 2015). "Foxp3+ regulatory T cells (Tregs) are often highly enriched within the tumor-infiltrating T cell pool." (PMID 26433463, 2015). "Expression of the inflammatory chemokine receptors, CCR1, CCR2, CCR3, CCR5 and CX3CR1, was significantly enriched on both Foxp3+ and Foxp3− CD4+ T cells within the tumours when compared with spleens and lymph nodes." (PMID 25495686, 2015).